BRD4 (bromodomain containing 4)
Diseases named in the same sentence as BRD4 in open-access papers (continued):
Sharing a sentence is not in itself a finding about the gene and the disease.
pulmonary arterial hypertension (7 papers, 2020 to 2025). Pulmonary arterial hypertension (PAH) is a group of diseases characterized by mean pulmonary artery pressure >20 mmHg and elevated pulmonary arterial resistance leading to right heart failure. "Increased BRD4 expression in coronary arteries of pulmonary hypertension patients contributes to vascular remodeling." (PMID 39090590, 2024). "BRD4 inhibition by JQ-1 and siRNA has been found to reverse vascular remodeling and enhance pulmonary hemodynamics in Sugen hypoxia-pulmonary arterial hypertension rats (SH-PAH), with decreased PAH SMC apoptosis resistance and proliferation." (PMID 37509171, 2023). "BRD4 expression is elevated in patients with idiopathic pulmonary arterial hypertension (PAH) and promotes the upregulation of polo-like kinase 1 (PLK1) via forkhead box M1 (FoxM1)." (PMID 39215370, 2024).
acute leukemia (6 papers, 2015 to 2025). A clonal (malignant) hematopoietic disorder with an acute onset, affecting the bone marrow and the peripheral blood. "ZBC260 induced degradation of BRD2, BRD3 and BRD4 at concentrations as low as 0.1–0.3 nM and downregulated c-Myc at 0.1 nM in the acute leukemia cell line RS4;11." (PMID 36986673, 2023). "Degrader 15 catalyzed the selective removal of BRD4 and BRD2, and effectively inhibited cell growth of human acute leukemia, breast cancer and non-small-cell lung cancer, with the GI50 values in the nanomolar range." (PMID 36986673, 2023).
atherosclerosis (6 papers, 2020 to 2026). A disease characterized by the build-up of fatty material and calcium deposition in the arterial wall resulting in partial or complete occlusion of the arterial lumen. "Altogether, we demonstrate for the first time that the formation of senescent macrophage in the BRD4-dependent epigenetic manner is one of the key contributors driving the initiation and progression of atherosclerosis." (PMID 32392533, 2020). "Inhibiting Brd4 and Pin1 expression alleviates enhancer-mediated inflammatory transcription and atherosclerosis, which indicates that BRD4 and PIN1 play a vital role in the development of vascular inflammation and atherosclerosis." (PMID 33148187, 2020). "More importantly, BRD4, a transcriptional regulator, mediates inflammatory transcription, atherogenic endothelial response, and atherosclerosis." (PMID 33148187, 2020). "Until recently, BRD4 was recognized to be potentially involved in several aging-related vascular diseases, such as atherosclerosis, aortic aneurysm, vascular neointima formation, PAH, and EH, indicating a potential aging-related epigenomic mechanism underlying the pathogenesis of vascular diseases." (PMID 37509171, 2023). "In addition, it has been shown that BRD4 participates in macrophage senescence and generates senescence-associated secretory phenotype (SASP), which furthers the development of atherosclerosis." (PMID 37509171, 2023). "In addition, siBRD4 and BRD4 inhibitors, such as JQ-1 and I-BET762, could protect the cells against LPS-induced senescence, indicating that BRD4 is a potential drug target for atherosclerosis and aging-related diseases." (PMID 32392533, 2020). "Therefore, it is possible that variants in BRD4 and PIN1 genes may lead to decreased vascular elasticity by destroying endothelial cells and causing atherosclerosis." (PMID 33148187, 2020). "Therefore, developing novel inhibitors targeting BRD4 could be a promising therapeutic strategy of atherosclerosis in clinical via preventing macrophage senescence." (PMID 32392533, 2020). "Two small molecule inhibitors of BRD4—namely, RVX208 (Apabetalone), which is in clinical trials for the treatment of atherosclerosis, and JQ1—were used to analyze the effect of BRD4 inhibition on endothelial inflammation and barrier integrity." (PMID 36364277, 2022). "We furtherly demonstrate that BRD4 takes part in macrophage senescence and gives rise to SASP, resulting in the progression of atherosclerosis." (PMID 32392533, 2020). "In a study that gathered a variety of macrophages from several sources, increasing BRD4 expression induced cellular senescence by encouraging the formation of SASP and the advancement of atherosclerosis-like conditions in the models with lipopolysaccharide (LPS) treatment." (PMID 37509171, 2023).
B cell lymphoma (6 papers, 2015 to 2024). "Although Brd4 has been associated with the IGH locus in B-cell lymphomas, it is unknown whether Brd4 is important for immunoglobulin production." (PMID 28322577, 2017). "The anti-proliferative properties of SRX3305 or SRX3262 (first-generation BTK/PI3K/BRD4 triple-inhibitor) were first evaluated in a panel of B-cell non-Hodgkin lymphoma (B-NHL) cell lines representative of CLL (OSU-CLL, HG-3, MEC-1, and MEC-2) and DLBCL (OCI-LY3 and SU-DHL-6)." (PMID 35743155, 2022). "Of note, BRD4 was also highly expressed in AML, T-ALL, B-ALL, and B cell lymphoma compared with that in other cancer cell lines." (PMID 35832114, 2022). "Among many other sites, BRD4 has been shown to bind superenhancers of the POUF2AF1 and BCL6 genes in B cell lymphoma lines." (PMID 28588024, 2017). "Western blot analysis from all B-cell lymphoma cell lines showed that BRD4, Myc and Bcl-2 protein expression was not altered following I-BET762 treatment over time." (PMID 26658189, 2015).
fibrosis (6 papers, 2021 to 2025). the formation of excess fibrous connective tissue in an organ or tissue in a reparative or reactive process. "In a relatively large scale of liver biopsy samples, qRT-PCR showed that BRD4 mRNA expression was significantly up-regulated in the fibrosis group compared with the expression in the control group." (PMID 34336890, 2021). "Western blot analysis also showed that the BRD4 protein level was significantly increased in the fibrosis group compared with the level in the control group." (PMID 34336890, 2021). "In this study, we used our novel, highly BD-selective chemistries to assess whether BRD4 BD1 plays a role in maintenance of bleomycin-induced fibrosis in mice." (PMID 35782526, 2022). "IHC analysis indicated that BRD4 expression was weak in healthy livers and remarkably increased in hepatocytes from MASH fibrosis patients." (PMID 38977508, 2024). "Bromodomain‐containing protein 4 (BRD4), part of the acetyl‐histone binding protein family, has emerged as a critical regulator of cardiac fibrosis activation through the TGF‐beta pathway." (PMID 38089921, 2023).
fragile X syndrome (6 papers, 2021 to 2024). A genetic syndrome caused by mutations in the FMR1 gene which is responsible for the expression of the fragile X mental retardation 1 protein. "Dysregulation of BRD4 has been causally linked to Rett Syndrome and fragile X Syndrome (FXS), two of the most prevalent neurodevelopmental disorders." (PMID 35615272, 2022). "Findings from animal studies showed a selective upregulation of BRD4 protein in an animal model of Fragile X Syndrome (FXS), a neurodevelopmental disorder that might cause intellectual disability or autism spectrum disorder." (PMID 34445411, 2021). "In a fragile X mental retardation 1 (Fmr1) knockout (KO) mouse, a model of autism spectrum disorder, fragile X syndrome (FXS), the level of BRD4 protein is elevated in the brain with widespread changes in chromatin regulation and aberrant gene expression." (PMID 34138732, 2021). "Similarly, in a mouse model of fragile X syndrome (FXS), BRD4 blockade alleviated the transcriptional dysfunction and the behavioral phenotypes associated with the disease." (PMID 36979729, 2023). "In a mouse model of fragile X syndrome (FXS), BRD2/3 and BRD4 showed oppositely altered expression and chromatin binding, correlating with transcriptional dysregulation." (PMID 34138732, 2021). "For example, CBP/p300 depletion in a fragile X syndrome (FXS) mouse model resulted in decreased binding of BRD4 but not BRD2/3 to promoters and enhancers of regulatory regions and rescued behavioral impairments." (PMID 38914477, 2024).
heart failure (6 papers, 2015 to 2025). Inability of the heart to pump blood at an adequate rate to meet tissue metabolic requirements. "BRD4 (Bromodomain-containing protein 4), a member of the bromodomain and extra terminal protein family, has been confirmed to play an important role in improving heart failure." (PMID 34925046, 2021). "Meanwhile, the inhibition of BRD4 with small molecules can reduce heart failure progression by regulating specific transcriptional programs." (PMID 32392533, 2020). "Moreover, they found that decreased BRD4 expression following heterozygous deletion results in delayed heart failure, which suggests that BRD4 may function as a critical protein scaffold in these cells via a bromodomain-independent mechanism." (PMID 36015180, 2022). "Furthermore, BRD4 could serve as a new target for regulating the phenotype of profibrotic cardiac fibroblasts and provide a potential therapeutic window suitable for the treatment of chronic fibrotic diseases such as heart failure." (PMID 32392533, 2020).
myocardial infarction (6 papers, 2020 to 2024). Gross necrosis of the myocardium, as a result of interruption of the blood supply to the area, as in coronary thrombosis. "Intriguingly, incremental BRD4 protein expression is recognized in cardiomyocytes in myocardial infarction, and its knockdown attenuates cardiomyocyte apoptosis." (PMID 37878982, 2023). "For example, one BRD4 inhibitor originally designed for cancer treatment, JQ1, was shown to be beneficial in mouse models of ischemic stroke, myocardial infarction, LPS-induced lung inflammation, and cisplatin-induced nephrotoxicity." (PMID 33348732, 2020). "Furthermore, the histone acetylation reader BRD4 undergoes genome-wide stimulus-dependent redistribution in cardiac fibroblasts, suggesting that the BRD4 inhibitor JQ1 could be used for the treatment of HF and myocardial infarction in the future." (PMID 39125279, 2024). "The vital roles of Brd4 and its inhibitor JQ1 have been proven in the epigenetic regulation of p300 in various profibrotic genes, such as NOX4, snail family transcriptional repressor 1 (SNAI1), and CTGF in IPF and myocardial infarction (MI) induced cardiac fibrosis." (PMID 36864460, 2023).
ovarian tumors (6 papers, 2017 to 2025). "BRD4 amplification and/or overexpression in ovarian tumors is often associated with a poor disease outcome." (PMID 34758842, 2021). "Subsequently, the corresponding genes of the total enriched proteins were analyzed in cBioportal (datasets of ovarian tumors) to identify highly mutated elements directly associated with the claudin-4-interacting proteins, revealing BRD4, CCDC130, PTK2, and NDRG1 as the most mutated elements." (PMID 38867360, 2024). "Although there have been attempts to characterize the oncogenic effect of BRD4 amplification in HGSOC, the exact mechanism by which BRD4 elicits ovarian tumor promotion is still a matter of scientific debate." (PMID 34758842, 2021). "Ovarian tumor models exposed to combination therapies such as ponatinib (TKi) and dBET1 (BRD4 degrader), or lapatnib (TKi) and AZD5153 (BETi) induced more robust cell apoptosis and tumor regression than each drug alone." (PMID 34758842, 2021). "Next, the putative circCELSR1/miR-598/BRD4 regulatory axis was examined in the in vivo ovarian tumors." (PMID 32640974, 2020). "PCAWG’s initial analysis of non-coding somatic drivers in over 2,600 cancer whole genomes identified breast and ovarian tumors with recurrent breakpoints in the BRD4 locus on chromosome 19p, which result in focal deletions that span gene regulatory regions and reduce global expression levels." (PMID 40112818, 2025). "Moreover, both the p-BRD4 and CSF1 levels correlated significantly with the numbers of TAMs in human ovarian tumors (r = 0.6976 and r = 0.4213, respectively)." (PMID 32286255, 2020).
periodontitis (6 papers, 2019 to 2022). An acute or chronic inflammatory process that affects the tissues that surround and support the teeth. "Both JQ1 and I-BET151 were small molecule inhibitors for BET proteins and JQ1 was demonstrated to attenuate inflammation and bone destruction in experimental periodontitis via neutralizing BRD4 enrichment at NF-κB, TNF-α, c-Fos, and NFATc1." (PMID 30455393, 2019). "In conclusion, our present data demonstrated that butyrate-induced ferroptosis may contribute to the loss of PDLFs during periodontitis development, and the onset of ferroptosis involves p38/HIF-1α activation and BRD4/CDK9 coordination." (PMID 33298848, 2020). "To gain insights into the pathologic role of CDK9 in the periodontitis, we first investigated the expression of CDK9, Brd4 and RNA Polymerase II, which coordinate in modulating gene transcription." (PMID 31758083, 2019).
autoimmune disease (5 papers, 2022 to 2025). A disorder resulting from loss of function or tissue destruction of an organ or multiple organs, arising from humoral or cellular immune responses of the individual to their own tissue constituents. "BRD4 has been widely studied in cancer, cardiovascular, metabolic, autoimmune diseases." (PMID 36721187, 2023). "Previous studies on BRD4 focused on cancer and autoimmune disease and have suggested that BRD4 may become a potential therapeutic target." (PMID 37509171, 2023). "Furthermore, considering the role of BRD4 in Tregs, modulating Treg functions by targeting BRD4 may have important therapeutic implications in autoimmune diseases and cancer therapies." (PMID 36256455, 2022).
cholangiocarcinoma (5 papers, 2019 to 2025). A carcinoma that arises from the intrahepatic biliary tree (intrahepatic cholangiocarcinoma) or from the junction, or adjacent to the junction, of the right and left hepatic ducts (hilar cholangiocarcinoma). "In cholangiocarcinoma cells, ARV-825 has been shown to significantly upregulate protein 21 expression in the G1 phase and prevent cell cycle progression, leading to the rapid and sustained degradation of BRD4 in cholangiocarcinoma." (PMID 36770884, 2023). "Although BRD4 inhibition has been proposed to induce apoptosis in cholangiocarcinoma cells, we did not detect significant apoptosis in cells in response to BRD4 inhibition." (PMID 32208449, 2020).
chronic myeloid leukemia (5 papers, 2019 to 2022). "Using this new approach, the authors demonstrated robust degradation of ERα, the chronic myeloid leukemia (CML)-causative BCR–Abl fusion protein, BRD4 and PDE4 proteins in cells." (PMID 31030225, 2019).
colitis (5 papers, 2020 to 2025). Inflammation of the colon. "Further analysis of such samples revealed that the induction of DSS-colitis was associated with enhanced expression of both IL-34 and BRD4, and samples extracted from colonic specimens of mice treated with JQ1 had a significant reduction in RNA transcripts for IL-34." (PMID 39451216, 2024). "A series of in vitro and in vivo experiments were conducted, and it was found that Berberine repressed pyroptosis and alleviated intestinal mucosal barrier defects caused by colitis, by inhibiting activation of Wnt/β-catenin signaling pathway by regulating miR-103a-3p/BRD4 axis." (PMID 35259053, 2022). "We also documented enhanced expression of BRD4 in the inflamed gut of mice with experimental colitis, and showed that BRD4 content paralleled the overexpression of inflammatory cytokines." (PMID 41311847, 2025). "Experiments have clarified BBR, elevated miR-103a-3p or repressive BRD4 was available to alleviate colitis-stimulated pyroptosis and intestinal mucosal barrier defects." (PMID 35259053, 2022). "Meanwhile, via further experimental verification, BBR functioned in colitis via modulating the miR-103a-3p/BRD4 axis." (PMID 35259053, 2022). "That is to say, BBR represses Wnt/β-catenin pathway activation via modulating the miR-103a-3p/BRD4 axis, thereby refraining pyroptosis and reducing the intestinal mucosal barrier defect induced via colitis." (PMID 35259053, 2022). "No separate exploration of Wnt/β-catenin signaling’ s function in colitis and the mechanism of miR-103a-3p/BRD4 modulating Wnt/β-catenin signaling is manifested." (PMID 35259053, 2022). "All in all, BBR represses Wnt/β-catenin pathway activation via modulating the miR-103a-3p/BRD4 axis, thereby mitigating colitis-stimulated pyroptosis and the intestinal mucosal barrier defect." (PMID 35259053, 2022). "Meanwhile, via further experimental verification, miR-103a-3p functioned in colitis via targeting BRD4." (PMID 35259053, 2022). "Elevated BRD4 was tested in DSS-induced colitis mice, which is the opposite of miR-103a-3p." (PMID 35259053, 2022). "Therefore, in the data it is the first to investigate the function and mechanism of BBR in colitis via miR-103a-3p/BRD4 axis, providing new insights into the pathogenesis of colitis." (PMID 35259053, 2022). "In the research, it was discovered BRD4 was elevated in colitis mice." (PMID 35259053, 2022). "Moreover, a reduction in BRD4 was discovered in the colon tissue of colitis mice elevating miR-103a-3p, elaborating that miR-103a-3p targeted BRD4." (PMID 35259053, 2022). "To further confirm the positive regulation of BRD4 on IL-34 expression in the gut, we analyzed the expression of the two proteins in the colons of mice with DSS-induced colitis." (PMID 39451216, 2024). "Here, it was aimed to investigate the functional role of BBR in colitis and the regulatory mechanism by which BBR repressed the activation of Wnt/β-catenin signaling pathway by regulating miR-103a-3p/BRD4 axis." (PMID 35259053, 2022). "BBR elevated miR-103a-3p to target BRD4; Refraining miR-103a-3p or enhancive BRD4 turned around BBR’s therapeutic action on colitis injury." (PMID 35259053, 2022). "Further studies will be needed to determine whether our findings on the hepatoprotective role of the FXR/BRD4 complex in cholestatic mice can be extended to the NASH and colitis models." (PMID 33290278, 2020).
esophageal cancer (5 papers, 2016 to 2025). A primary or metastatic malignant neoplasm involving the esophagus. "We analysed the correlation of AURKA or AURKB with BRD4 in oesophageal cancer using the GEPIA web‐based tool." (PMID 32954665, 2020). "Besides, the pharmacological inhibition of cyclin dependent kinase 7 (CDK7), bromodomain-containing protein 4 (BRD4) and histone deacetylases (HDACs), has been applied in esophageal carcinoma treatment." (PMID 36387198, 2022). "For another, it could also block recruitment of BRD4 on the promoter of aurora kinases A and B (AURKA/B) to trigger cellular senescence, which provided a novel action manner of BRD4 in esophageal carcinoma." (PMID 36387198, 2022). "Together, our data suggested that BRD4 inhibition induced cellular senescence by down‐regulating AURKA and AURKB in human oesophageal cancer cells." (PMID 32954665, 2020). "Similarly, in esophageal cancer models, we identified a significant association between mutation of the chromatin remodeling factor gene SMARCA4 and dependency upon the bromodomain protein BRD4 (p = 6 × 10−3), previously identified as a protein interaction partner of SMARCA4." (PMID 26947069, 2016).
gastric tumors (5 papers, 2021 to 2024). "BRD4, well-known for its role in super-enhancer organization and transcriptional activation, was elevated in gastric tumors and was correlated to inferior prognoses of GC patients." (PMID 36755269, 2023). "Taken together, these observations indicate that BET inhibitors, which potentially interfere with BRD4 recruitment to the ALDH1A3 promoter, decrease DTP cell survival and enhance chemotherapeutic efficacy against gastric tumors in vivo." (PMID 38669046, 2024). "With this approach we identified MDM2 ligase, coupled with inhibitors of the targets BCL2L1, BRD4, CDK9, PLK1 and MCL1 in stomach tumor tissue, as a therapeutic strategy." (PMID 35249548, 2022).